WNT5A (Wnt family member 5A)
Diseases named in the same sentence as WNT5A in open-access papers (continued):
Sharing a sentence is not in itself a finding about the gene and the disease.
melanoma (continued). "Upon long-term treatment with BRAFi, melanoma cell lines upregulate WNT5A expression." (PMID 36982422, 2023). "Finally, in co-culture assays, treatment with recombinant WNT5A was shown to dampen the reactivity of CTL to melanoma cells." (PMID 36982422, 2023). "The upregulation of WNT5A in BRAF inhibitor resistant melanomas could feasibly result from MAPK pathway reactivation, which would support an association between WNT5A and BRAFV600E signalling activity." (PMID 36539575, 2023). "Then, the researchers treated melanoma cells with recombinant sFRP1 and found that it could also inhibit WNT5A signaling, reduce the expression of dormant marker genes and increase the expression of proliferation markers." (PMID 36646673, 2023). "In particular, WNT5A is a well-defined feature of a poor melanoma phenotype and has been associated with a negative modulation of the tumor microenvironment." (PMID 37739939, 2023). "WNT5A has been demonstrated to inhibit the cell growth, migration and invasiveness of thyroid and colorectal cancer cells, while increased WNT5A expression is involved in the aggressiveness of other types of cancers, such as melanoma and gastric cancer." (PMID 36476423, 2022). "Overexpression of WNT5a in melanoma, gastric and pancreatic cancer increases metastasis." (PMID 36612190, 2022). "Furthermore, WNT5A expression is increased in the more aggressive BRAFi-R melanoma cells compared to their BRAFi-sensitive counterparts." (PMID 36551563, 2022). "Moreover, MANS peptide is able to suppress WNT5A-induced melanoma cell invasion in vitro by inhibiting MARCKS phosphorylation without affecting MARCKS expression." (PMID 36230850, 2022). "The aim of this study was to investigate whether the WNT5A downstream target MARCKS is an effective antimetastatic target in melanoma patients who have developed acquired resistance to BRAF inhibitors." (PMID 36551563, 2022). "Furthermore, inhibiting the Wnt5a/β-catenin/PPAR-γ axis not only decreased melanoma progression but also improved the efficacy of anti-PD-1 therapy." (PMID 36131916, 2022). "One such target could be myristoylated alanine-rich C-kinase substrate (MARCKS), a downstream target of WNT5A in BRAFi-sensitive melanoma cells." (PMID 36551563, 2022). "It has also been reported that phenotype switching in melanoma is regulated by the Wnt signaling pathway and that Wnt5A-treated B16 melanoma cells acquire greater metastatic and invasive potential, an effect mediated by the orphan tyrosine kinase receptor ROR2." (PMID 36135194, 2022). "Interestingly, Wnt5a signaling was engaged into melanoma cell movement, rendering them more aggressive." (PMID 35162934, 2022). "Taken together with the observation that WNT5A expression is significantly upregulated in BRAFi-R melanoma cells, we sought to investigate whether WNT5A-MARCKS signaling contributes to the increased invasiveness of BRAFi-R melanoma cells." (PMID 36551563, 2022). "ATG5 was able to manipulate a positive feedback loop between Wnt5a and autophagy in melanoma cells." (PMID 35194023, 2022). "Interestingly, the highest expression levels of WNT5A in the resistant melanoma cell lines were observed after exposure to PLX4720 (HTB63-R2 and A375-R2)." (PMID 36551563, 2022). "On the other hand, the top downregulated genes formed 4 subgroups and were related to melanogenesis (Wnt5a, Mitf, Pomc, Mc1r, Kit), melanoma (Fgf9, Fgf12, Fgf2), MAPK signaling pathway (Ncam1, Prkcb, Map3k4, Pla2g4a, Mapk14, Mapk11), and aging (Tgfbr1, Il6, Nox4)." (PMID 36555664, 2022). "We observed heterogeneity in expression of WNT5a in our samples, which may represent a heterogeneous population of aggressive, later-stage melanoma cells that have switched to a metastatic phenotype." (PMID 36230844, 2022).
melanoma (continued). "Notably, WNT5a expression has been shown to increase during melanoma progression, and correlates with poorer outcome." (PMID 36230844, 2022). "Clearly, whether and how WNT5A promotes the mesenchymal‐to‐amoeboid and amoeboid‐to‐mesenchymal transitions of melanoma cells and thus their invasiveness and metastatic potential are not clearly defined or understood." (PMID 33969605, 2021). "In melanoma cells, Wnt5a signaling enhances tumor angiogenesis, which involves a Ca2+-dependent release of exosomes containing pro-angiogenic proteins, VEGF and MMP2, whereas the promotion of exosomal secretion by Wnt5a can be inhibited by the calcium chelator Bapta." (PMID 34476217, 2021). "All these findings are in line with the hypothesis that RNF43 acts in melanoma as a tumor suppressor that restricts WNT5A-induced biological processes and gets silenced during melanoma progression." (PMID 34702444, 2021). "Indeed, syndecan-4 is an important component of the Wnt5A autocrine signaling loop and its overexpression is correlated to increased metastatic potential in melanoma patients." (PMID 33810567, 2021). "Thus, WNT5A has been suggested as a marker of progressive melanoma and a potential therapeutic target." (PMID 33969605, 2021). "However, during such inhibition of WNT5A signaling, some melanoma cells maintain their invasion ability." (PMID 33969605, 2021). "We then explored whether the reduced activity of Cdc42 is responsible for the impaired invasion of melanoma cells upon reduced WNT5A expression through gain‐of‐function experiments with the Cdc42 and Rac1 activator II." (PMID 33969605, 2021). "The noncanonical ligand WNT5A is associated with higher tumor grade and increased metastatic capabilities of melanoma cells." (PMID 33969605, 2021). "WNT5A signaling plays a crucial role in melanoma, one of the most malignant tumor types." (PMID 34702444, 2021). "Therefore, dual targeting of both WNT5A and RhoA signaling is more effective in inhibiting the invasion of these melanoma cells than targeting either of these signaling molecules alone." (PMID 33969605, 2021). "Melanoma-derived Wnt5a promotes the transcriptional expression of IDO1 in nearby DCs by Wnt5a-β-catenin signaling and activates peroxisome proliferator-activated receptor-γ (PPAR-γ) signaling pathway, culminating in enhanced IDO1 activity to establish an immunosuppressive microenvironment." (PMID 35003126, 2021). "Increased Wnt5a level promotes the ability of invasion in metastasis melanoma." (PMID 34108990, 2021). "Moreover, invasive growth of melanoma cells can be inhibited by syndecan-4 knockdown and rescued by addition of Wnt5a, suggesting an impact of syndecan-4 on this signaling pathway in melanoma." (PMID 33810567, 2021). "Wnt5a induction stimulated the release of proangiogenic Exo(s) from melanoma cells." (PMID 33207034, 2021). "Alternatively, RNF43/ZNRF3 KO could affect also canonical Wnt/β-catenin pathway that was shown to drive distinct features of melanoma cells than the ones related to the WNT5A-specific events." (PMID 34702444, 2021). "In conclusion, dual WNT5A and RhoA targeting could offer a more effective strategy for blocking melanoma cell invasion." (PMID 33969605, 2021). "However, rWNT5A stimulation of HTB63 cells, which have a low endogenous expression of WNT5A, triggered a distinct amoeboid‐to‐mesenchymal transition further supporting an essential role of WNT5A signaling in the regulation of melanoma cell plasticity." (PMID 33969605, 2021). "In conclusion, while WNT5A‐deficient melanoma cells exhibit reduced Cdc42 signaling and invasion, we also identified a counteracting response to this reduction in invasion in BRAF wild‐type and BRAFV600 mutated melanoma cells treated with a BRAF inhibitor." (PMID 33969605, 2021). "RNF43 inhibits WNT5A-dependent invasive properties of human melanoma." (PMID 34702444, 2021).
melanoma (continued). "The importance of WNT5A-driven signaling in melanoma is thus well recognized, and melanoma represents probably the most characterized (and most clinically relevant) pathophysiological condition where noncanonical WNT5A signaling drives cell invasion and disease progression." (PMID 34702444, 2021). "We analyzed WNT5A levels in two melanoma cell lines, that is, HTB63 and WM852 cells." (PMID 33969605, 2021). "Macrophage-derived exosomes containing Wnt5a activated the Wnt/β-catenin signaling pathway in breast cancer cells; this was further supported by the fact that Wnt5a increased exosome production in melanoma cells." (PMID 32252322, 2020). "However, characterizing the mechanism of WNT5A signaling in melanoma metastasis has proven to be challenging and, consequently, knowledge of the downstream molecular partners of WNT5A signaling is still incomplete." (PMID 32033033, 2020). "Interestingly, the Ser-159/163 phosphorylation of MARCKS was significantly decreased after WNT5A knockdown in HTB63 melanoma cells." (PMID 32033033, 2020). "At the same time, we checked the effect of WNT5A silencing on melanoma cell invasion." (PMID 32033033, 2020). "Moreover, KL inhibits Wnt5a-mediated filamin A cleavage through calpain, an effect contributing to reduced motility of melanoma cell lines." (PMID 33520985, 2020). "Additionally, it was reported that increased WNT5A signaling, which is known to promote melanoma metastasis, induced a Ca2+-dependent release of exosomes containing the pro-angiogenic VEGF and MMP2 factors in melanoma cells." (PMID 32709086, 2020). "Here, A2058 and A375 melanoma cells were exposed to 0.2 μg/mL recombinant WNT5A (rWNT5A) protein for different time periods (starting at 15 minutes to a maximum of 24 hr) to observe any changes in total expression and Ser-159/163 phosphorylation levels of MARCKS." (PMID 32033033, 2020). "We tested the effect of MANS and a control peptide on WNT5A-induced A2058 melanoma cell invasion." (PMID 32033033, 2020). "Another study showed that WNT5A can exert a dichotomous role in melanoma." (PMID 32238882, 2020). "In addition, the stimulation of melanoma cells with Wnt5a induces CD146 redistribution within polarized structures known as W-RAMP (Wnt5a-mediated receptor-actin-myosin polarity), leading to membrane retraction and cell migration in a RhoA-mediated mechanism." (PMID 33352759, 2020). "WNT5A overexpression leads to a significant increase in ATG5 mRNA levels in human melanoma cells." (PMID 32377431, 2020). "A2058 melanoma cells expressing very low amounts of WNT5A but with significant expression of the MARCKS protein were used to test whether the WNT5A-induced melanoma cell invasion was dependent on the presence of the MARCKS protein." (PMID 32033033, 2020). "Interestingly, WM852 melanoma cells which had higher WNT5A levels expressed significantly elevated amounts of MARCKS when compared to the other melanoma cell lines (HTB63, A375 and A2058 cells)." (PMID 32033033, 2020). "Moreover, WNT5A-induced invasion of melanoma cells was blocked by siRNA targeting MARCKS, indicating a crucial role of MARCKS expression and/or its phosphorylation." (PMID 32033033, 2020). "Interestingly, our results revealed a weak positive correlation between MARCKS and WNT5A mRNA expression in melanoma patient tissue." (PMID 32033033, 2020). "Another alternative downstream target of WNT5A-induced PKC signaling in melanoma cells that so far has only been used to monitor PKC activity in these cells is the phosphorylation of the endogenous PKC substrate myristoylated alanine-rich C-kinase substrate (MARCKS)." (PMID 32033033, 2020). "In the same way, WNT5A induced migration in chronic lymphocytic leukemia cells and melanomas." (PMID 33178184, 2020). "WNT5A-mediated Ca2+-dependent release of exosomes by melanoma cells has been reported." (PMID 32659938, 2020).
melanoma (continued). "Our study shed light on the previously unknown molecular events associated with WNT5A signaling that regulate MARCKS phosphorylation, which is crucial for melanoma metastasis." (PMID 32033033, 2020). "Endogenous Wnt5a in cells exert an immunomodulatory effect on melanoma by secreting chemokines." (PMID 33679872, 2020). "Furthermore, inducible overexpression of WNT5A in melanoma cells exhibiting low metastatic activity results in enhanced invasiveness, whereas siRNA-mediated knockdown of ROR2, the WNT5A receptor, reduced the frequency and severity of lung metastases in mice." (PMID 32659938, 2020). "This prompted us to directly test whether RhoA-ROCK signaling is also involved in WNT5A-mediated phosphorylation of MARCKS in melanoma cells." (PMID 32033033, 2020). "Furthermore, in contrast to the parental BRAFi‐sensitive melanoma cells, IL‐6 and WNT5A signalling independently promote the invasive migration of BRAFi‐R melanoma cells." (PMID 30582770, 2019). "In one of these two studies, the authors reported that the increased expression of WNT5A present in BRAFi‐R melanoma induces its effects through the Frizzled‐7 receptor, whereas the authors of a different study performed with a different setup reported that it occurred via the ROR2 receptor." (PMID 30582770, 2019). "Next, we investigated whether combined inhibition of both IL‐6 and WNT5A signalling had any effect on Cdc42‐GTPase or Rac1‐GTPase activity in BRAFi‐R melanoma cells." (PMID 30582770, 2019). "However, we identified that at least one such factor, IL‐6, increases melanoma cell expression of WNT5A through a p38‐MAPK signalling pathway." (PMID 30582770, 2019). "However, the IL‐6/WNT5A positive feedback loop present in parental melanoma cells is lost during development of acquired BRAFi resistance in melanoma cells." (PMID 30582770, 2019). "Surprisingly, however, we found that the IL‐6/WNT5A positive feedback loop present in parental melanoma cells was lost during the development of acquired BRAFi resistance, meaning that IL‐6 and WNT5A signalling were independent events in BRAFi‐R melanoma cells." (PMID 30582770, 2019). "Although not the primary focus of this study, we believe that using a blocking IL‐6 Ab and the WNT5A antagonist Box5, which will also restore the sensitivity of BRAFi‐R melanoma cells to BRAFi treatment, is a more relevant therapeutic approach from our perspective." (PMID 30582770, 2019). "However, because the BRAFi‐R melanoma cells secreted much more IL‐6 and expressed more WNT5A, we increased the dose of IL‐6 Ab and Box5 peptide to 2 μg·mL−1 and 200 μm, respectively." (PMID 30582770, 2019). "Furthermore, in a more recent report, we demonstrated that IL‐6 and WNT5A signalling constitute a positive feedback loop that potentiates the migration and invasion of melanoma cells." (PMID 30582770, 2019). "Conversely, Linnskog et al37 demonstrated a dose‐dependent increase in Wnt5a expression in IL‐6‐stimulated human melanoma cell lines, HTB63 and A375, whereas Box5, a peptide antagonist of Wnt5a, inhibited IL‐6‐induced cell migration and invasion of the melanoma." (PMID 31313518, 2019). "Since the NF-κB pathway is a master regulator of inflammation, we wanted to assess whether Wnt5a can increase the expression of cytokines and chemokines by melanoma cells." (PMID 31510045, 2019). "In summary, we show that Wnt5a, initially studied for its role in tumor migration and invasion, activates NF-κB and exerts an immunomodulatory role, further establishing Wnt5a as a promising therapeutic target for melanoma." (PMID 31510045, 2019). "In addition to reorganization of the actin cytoskeleton and polarized localization of cell adhesion molecules, others have shown that elevated Wnt5a expression promotes melanoma invasion and human biopsies directly correlated Wnt5a expression with tumor grade." (PMID 29648538, 2018).
melanoma (continued). "The non-canonical Wnt signaling pathway, mediated by WNT5A, has also been associated with increasing metastatic potential of melanoma cells and respective tumor grades." (PMID 30166456, 2018). "A loss of balance between G protein activation and deactivation has been implicated in the initiation of melanomas, and non-canonical Wnt signaling via the Wnt5A/Frizzled (FZD) pathway has been shown to be critical for the switch to an invasive phenotype." (PMID 30575751, 2018). "Thus, elucidation of the signaling events downstream of Wnt5a that promote polarized cell movement and metastatic behavior have the potential to enhance our understanding of the contribution of Wnt5a to melanoma metastasis." (PMID 29648538, 2018). "Our lab and others have shown Wnt5a signaling promotes migration and invasion in melanoma cells." (PMID 29648538, 2018). "Hypoxia can activate Wnt5A to induce melanoma stem phenotypic plasticity." (PMID 30340507, 2018). "Wnt5a expression is strongly correlated with melanoma progression and metastasis." (PMID 29648538, 2018). "Indeed, WNT5A has shown an important role in the invasive behavior of melanoma cells, since constitutive WNT5A overexpression is able to induce actin reorganization and increased cell adhesion." (PMID 30166456, 2018). "Moreover, melanoma cells express Wnt5a, which inhibits TLR-mediated pDC activation and IFN-I production." (PMID 29085361, 2017). "Overexpression of Wnt5a in melanoma correlates with chemotherapeutic resistance." (PMID 28484252, 2017). "Our data clearly indicate that WNT5A and IL-6 co-operate to facilitate melanoma cell migration and invasion and that the combined therapeutic inhibition of both WNT5A and IL-6 signalling stands out as an effective treatment strategy to prevent melanoma dissemination." (PMID 27191257, 2016). "Considering all of these factors, we have developed a WNT5A-derived antagonistic peptide that could be used to inhibit WNT5A signalling and subsequently reduce melanoma cell invasion." (PMID 27191257, 2016). "IL-6 induces WNT-5A in melanoma cells via p38 which, in turn, mediates cell migration." (PMID 26514730, 2016). "However, in other human tumors, such as melanoma and pancreatic cancer, Wnt5a increased tumor cell invasion and migration through actin reorganization, cell adhesion and epithelial to mesenchymal transition (EMT)." (PMID 27608847, 2016). "The binding of Wnt5a to FZD2 activates the Wnt/Ca2+ pathway in melanoma cell lines." (PMID 27323822, 2016). "Together, our results demonstrate that WNT5A and IL-6 are connected through a positive feedback loop in melanoma cells and that the combined targeting of both molecules could serve as an effective therapeutic means to reduce melanoma metastasis." (PMID 27191257, 2016). "For instance, melanoma cells released pro-angiogenic factor IL-6, vascular endothelial growth factor (VEGF) and MMP2, in a Wnt5a-dependent manner, and co-culture of Wnt5a-silenced melanoma cells with ECs showed decreased EC branching, compared with control melanoma cells." (PMID 27608847, 2016). "In addition, siRNA silencing of WNT5A expression and the inhibition of endogenous WNT5A signalling using Box5 significantly reduced IL-6 secretion in WM852 melanoma cells." (PMID 27191257, 2016). "To analyze whether WNT5A activates FZD7 in melanoma cells, we treated MA-2(shGFP) and MA-2(shFZD7) cells, or MeWo(shGFP) and MeWo(shFZD7) cells with recombinant WNT5A." (PMID 26808375, 2016). "This suggests a new oncogenic role for Wnt5a in inducing melanoma aggressiveness." (PMID 27571105, 2016). "Moreover, it has been demonstrated that WNT5A can positively regulate the exosomal release of IL-6, and we have shown that stimulation with exogenous IL-6 can induce WNT5A expression in malignant melanoma cells." (PMID 27191257, 2016).